IL21 (interleukin 21)
Diseases named in the same sentence as IL21 in open-access papers (continued):
Sharing a sentence is not in itself a finding about the gene and the disease.
emphysema (4 papers, 2012 to 2024). "A study on mice with pulmonary emphysema showed cigarette smoke to increase the percentage of IL-21+ Th17 and IL-21R+ CD8+ T-cells in peripheral blood, and to upregulate their expression of IL-17 and IL-21." (PMID 35386685, 2022). "Although these findings suggest that the enhanced Th17 cells and IL-21 production in emphysema are biologically relevant, the mechanism for Th17 cells in emphysema pathogenesis remains unidentified." (PMID 23319833, 2012). "In the present study, we hypothesized that Th17 cells and IL-21 are involved in the local and system inflammatory response using a murine model of emphysema induced by smoking." (PMID 23319833, 2012). "Thus, we presume that IL-21 released from Th17 cells might play a more important role in the immunopathology of emphysema through its actions on CD8+ T cells." (PMID 23319833, 2012). "More importantly, a significantly positive correlation between the number of IL-21+Th17 and CD8+IL-21R+ T cells and emphysematous lesions was found in CS-exposed mice, which indicated the importance of IL-21+Th17 and CD8+IL-21R+ T cells in the development of emphysema." (PMID 23319833, 2012). "In addition, IL21 produced by CD4+ T cells could promote a Th1/Tc1 response, leading to systemic inflammation in emphysema." (PMID 38612871, 2024).
Hashimoto thyroiditis (4 papers, 2013 to 2023). An autoimmune disorder caused by the production of autoantibodies against thyroid tissue. "SNPs of the IL-21 gene have been found to be associated with development of GD, while individuals with SNPs at the common IL-21 and IL-21R genes may present a higher risk of developing Hashimoto’s thyroiditis." (PMID 25667655, 2015).
immunodeficiencies (4 papers, 2008 to 2025). "Nevertheless, immunodeficiency is one condition caused by loss of function mutations in the IL21 and IL21R genes." (PMID 40004558, 2025). "Since γc is shared by receptors for IL-4, IL-7, IL-9, IL-15, and IL-21 and a loss of γc function causes immunodeficiencies in both humans and mice, it is anticipated that knockdown of γc may lead to severe systemic side effects." (PMID 24223832, 2013). "The molecular cause for the selectively impaired production of IL-21, IL-4, and IL-10 is not understood yet, but the high expression of PD-1, a negative regulator of T cell activation might interfere with cytokine secretion and contribute to the immunodeficiency." (PMID 29375547, 2017).
ischemia (4 papers, 2020 to 2022). A hypoperfusion of the BLOOD through an organ or tissue caused by a PATHOLOGIC CONSTRICTION or obstruction of its BLOOD VESSELS, or an absence of BLOOD CIRCULATION. "In summary, we have demonstrated that a novel angiogenic IL-21/IL-21R/miR-30b/STAT3 promotes endothelial cell survival under ischemia in PAD." (PMID 35008699, 2021). "CD4+ T cells and natural killer T (NKT) cells produce IL-21, and augmented concentrations of brain IL-21 following experimental ischemia occurs after lymphocyte infiltration." (PMID 32185190, 2020). "Furthermore, we found that miR-30b, a molecule which is required for IL-21-induced angiogenesis under ischemia, also increases STAT3 activation with reduced SOCS3 expression." (PMID 35008699, 2021). "It should be noted that several other interleukins such as IL-19 and IL-21 also contribute to myocardial injury during ischemia, so we may need more investigation on them in the future." (PMID 32293300, 2020). "The serum levels of interleukin (IL)-17A and IL-21 were decreased, and the expression of JAK2/STAT3 proteins was inhibited in all RJQM treatment groups compared to the ischemia group." (PMID 36034959, 2022).
juvenile idiopathic arthritis (4 papers, 2010 to 2024). Juvenile idiopathic arthritis (JIA) is the term used to describe a group of inflammatory articular disorders of unknown cause that begin before the age of 16 and last over 6 weeks. "This is in accord with a recent report in juvenile idiopathic arthritis demonstrating that clonally expanded IL21 and IFNG co-expressing Tph promote CD11c+ double negative B cell differentiation." (PMID 38862501, 2024).
myocarditis (4 papers, 2016 to 2023). Myocarditis is a condition that is characterized by inflammation of the heart muscle (myocardium). "Another study investigated IL-21 signaling in the context of CVB3-induced myocarditis and concluded that IL-21 mediate excessive activation of CD8+ T cells, thereby contributing to inflammation." (PMID 31401790, 2019). "The expression levels of IL-21 and IL-22 are markedly increased in acute virus-induced myocarditis (AVMC), and IL-22 exacerbates the severity of AVMC20." (PMID 27198976, 2016). "CVB3-infected CD8−/− mice had attenuated myocarditis symptoms when transferred with CD8+ T cells from WT mice instead of IL-21 R−/− mice, suggesting that IL-21 R signalling regulates viral myocarditis via activation of CD8+ T cells." (PMID 36827455, 2023).
plaque psoriasis (4 papers, 2015 to 2023). "Overall, IL-21 and its receptor were highly expressed in CD4+ T cells in the lesional skin of moderate-to-severe plaque psoriasis patients." (PMID 31440249, 2019). "Thus, we detected the expression of ICOS, PD-1, HLA-DR, and Ki-67 on cTfh cells and secretion of IL-21, IL-17, IFN-γ, and IL-10 by cTfh cells in patients with psoriasis vulgaris." (PMID 27774460, 2016). "Compounds targeting IL-23 and IL-21 have been or are under investigation in plaque psoriasis and chronic inflammatory arthritides, but not yet in pSS." (PMID 26060357, 2015).
pulmonary fibrosis (4 papers, 2023 to 2026). Chronic progressive interstitial lung disorder characterized by the replacement of the lung tissue by connective tissue, leading to progressive dyspnea, respiratory failure, or right heart failure. "Furthermore IL-21 expression was found to be elevated in the lungs of Idiopathic pulmonary fibrosis (IPF) patients compared to controls." (PMID 41691089, 2026). "In addition, the expression of IL-21 receptor (IL-21R) is detected in infiltrating lymphocytes of human pulmonary fibrosis specimens, suggesting that IL-21-responsive lymphocytes might be related to the progression of pulmonary fibrosis." (PMID 37628716, 2023). "IL-21 is a key cytokine for differentiation of CD8 T into Tc2 cells, demonstrating that CD8 T is involved in pulmonary fibrosis in an IL-21-dependent manner." (PMID 38609879, 2024).
Splenomegaly (4 papers, 2015 to 2026). Abnormal increased size of the spleen. "Myeloid-specific Znrf1 deletion caused age-dependent spontaneous splenomegaly and, upon allosensitization, elevated CD4+/CD8+ T-cell ratios, enlarged germinal centers with heightened IL-21/Tfh activity, and augmented alloantibody production." (PMID 41896526, 2026). "Despite increased anemia and splenomegaly, neither Il21-/- nor Il21r-/- mice had any other clinical signs." (PMID 25763578, 2015).
thyroiditis (4 papers, 2022 to 2025). Inflammation of the thyroid gland. "We recently identified IL-21+ T follicular helper (Tfh) cells as critical mediators of ICI-thyroiditis, another common endocrine IrAE seen in 15%–25% of patients treated for ICI." (PMID 40626363, 2025). "Furthermore, in individuals with ICI-thyroiditis, IL-21+ CD4+ Tfh cells are key drivers of thyroid autoimmune attack." (PMID 40626363, 2025). "We found that thyrotoxic IFN-γ+CD8+ T cells in the thyroid were driven by IL-21 from CD4+ Tfh cells and inhibition of IL-21 prevented ICI-thyroiditis." (PMID 40626363, 2025). "While a role for IL-21 in ICI-T1DM has not been described, we showed in mice and humans with ICI-thyroiditis that IL-21 from CD4+ cells could augment effector molecules (IFN-γ, granzyme B) and chemokine receptors on thyrotoxic CD8+ T cells." (PMID 40626363, 2025).
toxoplasmosis (4 papers, 2010 to 2017). A parasitic disease contracted by the ingestion or fetal transmission of toxoplasma gondii. "Thus, the role of IL-21 in regulating multiple inhibitory receptors during chronic Toxoplasmosis is very important and needs to be further investigated." (PMID 29163509, 2017). "Therefore, in the next series of studies, we determined the role of IL-21 in CD8 T cell functionality during chronic Toxoplasmosis using IL-21R KO animals." (PMID 29163509, 2017). "Additionally, IL-21 has been associated with the differentiation of IL-10 producing CD4+ T cells, which contribute to limiting immune-mediated pathology during toxoplasmosis." (PMID 23667536, 2013). "Therefore, experiments were performed to reevaluate the function of IL-21 during toxoplasmosis." (PMID 23667536, 2013). "Apart from IL-7 and IL-15, potential role of other γc family members like IL-4 and IL-21 that have been implicated in CD8 memory generation in other infectious disease models, need to be considered in future investigations of memory CD8+ T cell development during toxoplasmosis." (PMID 20520779, 2010).
vasculitis (4 papers, 2013 to 2024). "Those with vasculitis (n=4) had significantly reduced IL-21 levels and FC of miR-124 (253 ± 147.4 and 0.04 ± 0.05 vs 586.3 ± 410.5 and 0.54 ± 0.8; p=0.008 and p=0.001, respectively)." (PMID 39464895, 2024). "Based on the studies in various forms of vasculitis it is therefore conceivable that IL-21 together with IL-17 plays a critical role in the pathogenesis of AAV." (PMID 25352848, 2014). "Additionally, we observed lower FC of miR-146a in patients with pulmonary manifestations, miR-21 in patients with GIT involvement, IL-21 and miR-124 in those with vasculitis, and IL-12 and miR-124 in those with thrombosis." (PMID 39464895, 2024). "The role of IL-21 in vasculitis was previously suggested by Chen and coworkers." (PMID 23799890, 2013).
acute GVHD (3 papers, 2013 to 2022). "Previously, our group proposed that blockade of the IL-21 signaling pathway reduces BAFF-induced downregulation of pathogenic T- and B-cell function through the Akt–mTORC1–p70S6 kinase pathway in an acute GVHD model." (PMID 36561743, 2022). "Previous studies focused primarily on the regulation of BAFF through the blockade of IL-21 in acute GVHD." (PMID 36561743, 2022). "Our group has reported that the blockade of BAFF through belimumab therapy or blocking of IL-21 signaling plays critical roles in the generation of CD4+CD25+Foxp3+ Treg cells in acute GVHD after allo-BMT." (PMID 36561743, 2022). "The main purpose of this study was the evaluation of IL-21, as a blood biomarker, for early detection of acute GVHD (aGVHD) in children after HSCT and also the study of human leukocytes antigen (HLA)-C1 polymorphism, as a targeting ligand for NK cells in these patients." (PMID 28627158, 2017). "Many approaches have been developed and are being under investigation to prevent and treat acute GVHD using experimental models, including IL-21 blockade, Histone deacetylase inhibitors inducible costimulator, CSF-1, glycogen synthase kinase 3 inhibotion, Human CD8+ Regulatory T Cells." (PMID 23802653, 2013).
Acute Hepatitis C (3 papers, 2013 to 2023). "have reported in the context of Hepatitis C a balance between Gal-9 released by Tregs and IL-21 released by Th17 cells, with a capacity of IL-21 to protect effector CD4+ and CD8+ T cells from cell death and/or exhaustion induced by Gal-9." (PMID 36817445, 2023).
allergic rhinitis (3 papers, 2017 to 2022). Inflammation of the nasal mucous membranes caused by an IgE-mediated response to external allergens. "IL-21 has an anti-allergic effect, evidenced by its role in the remission of allergic rhinitis in mice." (PMID 32143340, 2020).
alopecia areata (3 papers, 2021 to 2025). Loss of scalp and body hair involving microscopically inflammatory patchy areas. "To date, genome-wide association studies identified only a few susceptibility loci for alopecia areata associated with Th cytokines such as IL-2/IL-21 and IL-13." (PMID 34943905, 2021). "It found that people with alopecia areata had increased plasma levels of the Type 2 cytokines IL-33, IL-31 and IL-17E (IL-25), in addition to the Type 17 cytokines IL-17A, IL-21, IL-23 and IL-17F." (PMID 38892934, 2024). "The mean serum levels of IL-6, TNF-α, IL-17A, and IL-21 were comparable between the two sexes, with p values exceeding 0.05, indicating that gender did not appear to influence the systemic inflammatory response in alopecia areata." (PMID 41002719, 2025). "Alopecia areata is characterized by systemic dysregulation of Th1 (IL-2, IFN-γ, TNF and IL-12), Th2 (IL-6), and Th17 (IL-17, IL-21) cytokines." (PMID 34943905, 2021). "Based on our analysis, it may be suggested that alopecia areata is characterized by the dysregulation of systemic Th1 (IL-2, IFN-γ, TNF and IL-12), Th2 (IL-6), and Th17 (IL-17, IL-21) cytokines." (PMID 34943905, 2021).
Alzheimer disease (3 papers, 2022 to 2025). A progressive, neurodegenerative disease characterized by loss of function and death of nerve cells in several areas of the brain leading to loss of cognitive function such as memory and language. "In Alzheimer’s Disease, increased IL-21 levels lead to increased expression of MHC II in spleen Mφ and secretion of a large number of pro-inflammatory cytokines such as IL-18, TNFα and IL-1β." (PMID 37628738, 2023).
anaphylaxis (3 papers, 2009 to 2023). An acute hypersensitivity reaction that occurs from exposure to an allergen. "The administration of recombinant mouse IL-21 or an IL-21 expression plasmid suppressed anaphylaxis in mice previously sensitized to peanut." (PMID 23282314, 2009). "In another study, the investigators examined whether IgE-mediated systemic anaphylaxis was controlled by the in vivo administration of IL-21 using a mouse model of peanut-induced anaphylaxis." (PMID 25531161, 2014).
anemia (3 papers, 2015 to 2024). A reduction in the number of red blood cells, the amount of hemoglobin, and/or the volume of packed red blood cells. "The non-resolving P. chabaudi infection was accompanied by increased anemia in both Il21-/- and Il21r-/- mice from days 19–22 post-infection onwards." (PMID 25763578, 2015).
antibody deficiencies (3 papers, 2017 to 2025). "Thus, our work provides further insight into the unraveling of the previously hypothesized role of IL-21 to reconstitute immunoglobulin production in primary antibody deficiencies." (PMID 30936864, 2019). "Although our patient presents CD4+ T cell lymphopenia and antibody deficiency, we assessed normal CD4+ and CD8+ cell proliferation with CD3/CD28 and in B cells with both T cell dependent stimuli (CD40L and IL-21) and the combination of T cell dependent and independent stimuli." (PMID 40170851, 2025). "Addressing the initial hypothesis, our experimental data suggests that antibodies against the cytokines BAFF, ARIL, and IL-21 do not play a role in the pathogenesis of primary antibody deficiencies." (PMID 28651547, 2017).
autoimmune encephalitis (3 papers, 2019 to 2025). Inflammation of the brain secondary to an immune response triggered by the body itself. "This expression could best be explained by the presence of T-follicular-helper cells which, through interleukin 21, can trigger a TH-2-dominated immune response and lead to autoimmune encephalitis." (PMID 40440345, 2025).
autoimmune gastritis (3 papers, 2018 to 2024). Inflammation of the body fundic mucosa of the stomach. "These initial findings suggest that IL-21 may play a critical role in the advancement of autoimmune gastritis but requires studies to determine whether IL-21 overexpression is a primary promoter of AIG." (PMID 39193325, 2024). "In animals with autoimmune gastritis, IL-21 and TNF-alpha are highly expressed." (PMID 30127260, 2018).
autoimmune myocarditis (3 papers, 2020 to 2023). Autoimmune myocarditis is an autoimmune disease that affects the heart. "Our results indicated that overexpression of Tfh cells (including Tfh1, Tfh2 and Tfh17) in autoimmune myocarditis might lead to the increased secretion of IL‐21, causing autoimmune myocarditis to produce excess autoantibodies." (PMID 32416035, 2020). "The expression levels of IL‐21 and CXCL13 were elevated in the serum and spleen of rats with autoimmune myocarditis." (PMID 32416035, 2020). "Furthermore, we also observed the expression of cytokine IL‐21 and chemokine CXCL13 in the spleen of rats with autoimmune myocarditis." (PMID 32416035, 2020). "Furthermore, our findings suggested that Tfh cells could generate a large number of cytokines IL‐21 and CXCL13 to stimulate B cells to produce a large number of autoantibodies, which ultimately accelerates the development of autoimmune myocarditis." (PMID 32416035, 2020).
autoimmune uveitis (3 papers, 2009 to 2021). An autoimmune form of uveitis (disease). "In summary, our study showed that increased IL-21 production and elevated IL-21R expression may be associated with the development of autoimmune uveitis in mice." (PMID 20057909, 2009). "Our study is designed to investigate the alteration and possible function of IL-21 in the development of an experimental autoimmune uveitis (EAU) model." (PMID 20057909, 2009). "With the suggestion that the IL-21–IL-21R pathway may be involved in the pathogenesis of autoimmune uveitis, we propose a possible therapeutic approach for autoimmune uveitis through the manipulation of IL-21 secretion." (PMID 20057909, 2009).
Behçet’s disease (3 papers, 2013 to 2025). "The role of IL-21 has been demonstrated in Behçet disease, a form of variable vessel vasculitis." (PMID 25352848, 2014).
brain tumour (3 papers, 2017 to 2025). "This antigen-specific response was further amplified in patients with brain tumor upon conditioning of whole blood with IL-2/IL-15/IL-21." (PMID 29970101, 2018). "We therefore concluded that the mesothelin-specific response of patients with grade IV brain tumors has potential to be enhanced with IL-2/IL-15/IL-21 conditioning." (PMID 29113296, 2017). "In the reanalysis, we found that patients with grade IV brain tumour (GBM), constituting the majority of group of the study cohort, exhibited a significantly increased IFN-γ response to MPF and mesothelin precursor peptide pool if the PBMCS were conditioned with IL-2/IL-15/IL-21." (PMID 29113296, 2017).
Burkitt lymphoma (3 papers, 2017 to 2024). A rare form of malignant mature B-cell non-Hodgkin lymphoma. "In this manner, IL-21 treatment could not only induce LMP1 expression in Burkitt tumors, but could also enhance cellular immune responses to EBV-infected tumor cells." (PMID 38683861, 2024). "IL-21 induces LMP-1 expression, as well as activation of the host STAT3, in a type I latency Burkitt lymphoma cell line and in a conditional LCL9." (PMID 32704112, 2020). "Specifically, IL-21 treatment of type I latency Burkitt lymphoma cells inhibits cell proliferation, whereas in type III latency LCL and Burkitt lymphoma cell lines it induces plasma cell differentiation." (PMID 32704112, 2020).
Cerebral ischemia (3 papers, 2018 to 2022). Restriction of arterial blood supply to the brain associated with insufficient oxygenation to support the metabolic requirements of the tissue. "In contrast, downregulation of IL-21 conferred resistance and neuroprotection against experimental brain ischemia in rats." (PMID 32185190, 2020). "Increased IL-21 was also observed in the injured mouse brain after cerebral ischemia." (PMID 35648273, 2022). "More recently, IL-21 was found to be highly upregulated in the mouse brain after cerebral ischemia." (PMID 30115117, 2018).
cognitive deficits (3 papers, 2018 to 2025). "In contrast, the levels of IgG as well as interleukin-21, the major cytokine involved in class switching, were increased in AD and patients with mild cognitive impairment, indicating a strong immune response against Aβ." (PMID 30115117, 2018). "Increased IL-21 in early stages may therefore, be enhancing Aβ deposition in the brain that leads to cognitive deficits." (PMID 35648273, 2022).